DYRK2 (dual specificity tyrosine phosphorylation regulated kinase 2)
Diseases named in the same sentence as DYRK2 in open-access papers (continued):
Sharing a sentence is not in itself a finding about the gene and the disease.
cancer (continued). "Genetically modified mouse models have provided information regarding the function of DYRK2 in various cancers." (PMID 37886981, 2023). "One of the main purposes of this review on DYRK2 was to discuss the potential of DYRK2 as a new target for cancer treatment." (PMID 37886981, 2023). "Targeting DYRK2 has proven to be a tractable strategy to target cancers sensitive to proteotoxic stress; however, the development of HSF1 inhibitors remains in its infancy." (PMID 36622366, 2023). "Cell line and/or xenograft mouse model studies have been conducted to elucidate the mechanism of DYRK2 function in certain cancers." (PMID 37886981, 2023). "The reported duality in the functions of DYRK2 in various cancers has complicated our understanding of DYRK2 function in tumors." (PMID 37886981, 2023). "The current study establishes that concurrent targeting of HSF1 and DYRK2 can indeed impede cancer by inducing apoptosis faster than individual targetting." (PMID 36622366, 2023). "In fact, expressions of HSF1 and DYRK2 seem to cluster together during chemotherapy response or at predicting response to cancer monotherapies." (PMID 36622366, 2023). "Overall, multiple independent databases seem to agree that HSF1 and DYRK2 expressions overlap and correlate in diverse cancer models and also in responses to chemotherapies." (PMID 36622366, 2023). "In particular, studies using genetically modified mice would help us to understand the reported functional duality of DYRK2 in cancer." (PMID 37886981, 2023). "Through further study of DYRK2, it can be used to guide clinical practice and provide new ideas for cancer treatment." (PMID 36104345, 2022). "DYRK2 has been reported to trigger antitumor and pro-apoptotic signals, while in parallel other studies identified DYRK2 as a highly overexpressed kinase in various cancer types and DYRK2 inhibitors were shown to exhibit antiproliferative properties." (PMID 35719374, 2022). "DYRK2 is overexpressed in various cancer types and is involved in the proteo-stasis pathway that can enhance cancer cells survival under stressful conditions." (PMID 35454940, 2022). "Together, these results confirm that 4E-BP1 is a direct cellular target of DYRK2 and suggest the potential use of DYRK2 inhibitors in combination with other kinase inhibitors for cancer therapy." (PMID 35439114, 2022). "At the same time, we found that DYRK2 methylation plays a dual role, both carcinogenic and suppressive in some cancers." (PMID 36104345, 2022). "Although several DYRK2 inhibitors were discovered and exhibited anti-cancer activity in MM and TNBC31,32, their selectivity over DYRK family members and drug-like properties need to be further modified." (PMID 35614066, 2022). "This research performed extensive cancer analyses of DYRK2 by TCGA project and GEO database.Research is carried out on gene expression levels, protein phosphorylation levels, gene mutation profiles and immune infiltration in various types of cancer." (PMID 36104345, 2022). "TCGA data showed that the DYRK2 gene was altered at different loci in distinct cancers, and in most cancer types, the alteration of DYRK2 gene was mainly amplified." (PMID 36104345, 2022). "From the class 2 DYRK subgroup, only DYRK2 was extensively studied in terms of tumorigenesis and found to have a controversial role in cancer." (PMID 35454940, 2022). "In order to fully understand the role of DYRK2 in different tumors, we conducted a pan-cancer analysis." (PMID 36104345, 2022). "In general, low DYRK2 expression correlates with shorter survival, invasiveness, cancer recurrence or poor prognosis." (PMID 34363019, 2022).
cancer (continued). "Considering the critical function of DYRK2 in cancers, we conducted a data-mining of TCGA to find the high expression of DYRK2 in PCa, which was positively correlated with clinical prognosis and mortality." (PMID 35614066, 2022). "The correlation between the expression level of DYRK2 and the prognosis of different cancer patients was obtained through TCGA and GEO datasets." (PMID 36104345, 2022). "DYRK2 maintains protein stability in cancer cells by promoting proper protein folding or degradation." (PMID 36104345, 2022). "SIAH2, in turn, is capable of degrading DYRK2 in specific cancers thereby triggering a protumorigenic hypoxic microenvironment." (PMID 33376136, 2021). "Various global unbiased studies in various cancers have reported DYRK2 as a potential cancer driver with increased copy numbers, overexpression, and higher activity." (PMID 33376136, 2021). "DYRK2 maintains proteostasis of cancer cells by regulating two major players of the proteotoxic response pathway, which promotes the proper folding and/or degradation of proteins." (PMID 33376136, 2021). "The DYRK2 promoter region exhibited a higher level of methylation in cancer tissues than healthy tissues while treatment of cells with hypomethylating drug 5-azacytidine increased DYRK2 mRNA and protein levels." (PMID 33376136, 2021). "A major paradigm shift occurred in the last 4 years when DYRK2 was found to regulate proteostasis in cancer via a two-pronged mechanism." (PMID 33376136, 2021). "To reiterate, multiple molecular mechanisms have been proposed for DYRK2, and each mechanism is cancer-type or subtype specific." (PMID 33376136, 2021). "We found that DYRK2 gene and protein was markedly low abundant in cancer tissues, but GIL2 was just distinct stronger in gene lever, not in protein lever." (PMID 33995647, 2021). "Other functions like cancer stem cell formation and epithelial–mesenchymal transition regulation are also controlled by DYRK2." (PMID 32462403, 2020). "In keeping with its effect on the interaction with CDPs, the non-cancer-related Dyrk2 KR mutant showed a rather minor effect on the phosphorylation of CDPs." (PMID 32678104, 2020). "Cell survival: Studies conducted in different cancer patients show that DYRK2 correlates with the survival rate according to the specific cancer subtype." (PMID 32462403, 2020). "We show that DYRK2 regulation by chemotherapeutic agents has a relevant effect on the viability, motility and invasion capacity of cancer cells expressing NOTCH1." (PMID 31605148, 2020). "Cancer stem cell (CSC) formation: To date there are several studies relating DYRK2 expression with this relevant cell population." (PMID 32462403, 2020). "Altogether, these results indicate a new role of DYRK2 in cancer cell migration/invasion through the regulation of Notch1-IC levels." (PMID 31605148, 2020). "DYRK2 modulates functions as important in cancer development as apoptosis, cell proliferation, or cell growth, among others." (PMID 32462403, 2020). "The relevance of this interaction is highlighted by the alterations in the assembly of the EDVP complex detected in the analysis of certain DYRK2 mutants found in cancer samples." (PMID 32751160, 2020). "Other diseases: Together with the efforts to elucidate the regulatory mechanisms and implications of DYRK2 in cancer, the role of this kinase in other pathologies has been studied." (PMID 32462403, 2020). "DYRK2 roles in diseases have been studied in detail, highlighting this kinase as a key protein in cancer development." (PMID 32462403, 2020). "In combination, AP–MS and BioID–MS confirmed the composition of the Dyrk2 kinase core complex and provided an extended interaction network, which is enriched in cancer driver proteins and processes, as well as other functions." (PMID 32678104, 2020). "p-value ≤ 0.05) and the non-cancer-related, catalytically inactive kinase mutant (Dyrk2 KR, 21 interaction changes with │log2FC│ > 1 and adj." (PMID 32678104, 2020).
cancer (continued). "Several studies highlighted the importance of DYRK2 impairing the development and progression of human cancers, such as non-small cell lung cancer, esophageal adenocarcinomas, breast cancer and ovarian serous adenocarcinoma." (PMID 31605148, 2020). "MiR-622: MiR-622 is downregulated in CRC and suppresses migration, invasion, and proliferation of cancer cells by targeting various targets such as dual-specificity tyrosine phosphorylation-regulated kinase 2 (DYRK2) and Kirsten rat sarcoma (K-Ras)." (PMID 31887997, 2019). "Moreover, the disruption of 26S proteasome activity induced by curcumin through inhibiting DYRK2 in different cancerous cells resulting in the inhibition of cell proliferation opens up a new horizon for using curcumin as a potential preventive and treatment approach in proteasome-linked cancers." (PMID 31214247, 2019). "Inactivation of DYRK2 sensitized these cancer cells to the proteasome inhibitor Bortezomib in vitro, and blockade of Rpt3-T25 phosphorylation significantly attenuated their tumorigenecity in vivo." (PMID 28258412, 2017). "DYRK2 has a critical influence on the development and advancement of cancer." (PMID 38474160, 2024). "Since then, the number of DYRK2 studies in cancer has increased." (PMID 37886981, 2023). "Here, we review the functions of DYRK2 in various cancers and elucidate the current understanding." (PMID 37886981, 2023). "This discrepancy makes it difficult to elucidate the conserved functions of DYRK2 in cancer." (PMID 37886981, 2023). "However, the role of DYRK2 in cancer remains controversial as there are two opinions regarding DYRK2 function." (PMID 37886981, 2023). "Moreover, the development of a new cancer drug that targets DYRK2 requires animal experiments to determine drug efficacy, the presence or absence of side effects, and delivery routes." (PMID 37886981, 2023). "Therefore, we performed a detailed investigation into the mechanism by which DYRK2 functions in different cancers both in vitro and in vivo to determine the exact role of DYRK2 in cancer." (PMID 37886981, 2023). "This further adds traction to our hypothesis that pharmacological inhibition of HSF1 in combination with DYRK2 inhibitors could induce enhanced cytotoxicity in cancer cells while also sensitise bortezomib-resistant cells." (PMID 36622366, 2023). "The DYRK2 overexpression tumors were lymphocytes, and the control tumors were mostly cancer cells." (PMID 37886981, 2023). "Hence, DYRK2 targeting in various cancers have been gaining traction over the last 5 years since our work asserted the protumourigenic role of the kinase." (PMID 36622366, 2023). "Here, we reviewed the functions of DYRK2 in various cancers." (PMID 37886981, 2023). "Overall, it is difficult to determine whether a sufficient number of studies have been published to determine the function of DYRK2, particularly as an oncogene in cancer." (PMID 37886981, 2023). "Moreover, DYRK2 has been proposed as a potential prognostic marker for cancer and metastasis and as a predictive marker for clinical responses to cancer treatment." (PMID 34363019, 2022). "So, our comprehensive approach includes a pan-cancer analysis of DYRK2 based on data from TCGA." (PMID 36104345, 2022). "Thus, it is urgent to reveal the function of DYRK2 in PCa and develop DYRK2 inhibitors with better potency and higher selectivity to treat PCa and other cancers." (PMID 35614066, 2022). "Since DYRK2 plays critical roles in various human cancers, targeting DYRK2 could also provide a promising opportunity for other patients with refractory cancers." (PMID 35614066, 2022). "These researches revealed the critical and multifarious roles of DYRK2 in different cancers." (PMID 35614066, 2022). "Therefore, it is of great significance to investigate the latent relationship between different immune cell infiltration levels and DYRK2 expression in TCGA of different cancer types through a series of algorithms." (PMID 36104345, 2022).
cancer (continued). "Thus, over the past few decades, many groups have identified various molecular mechanism and substrates for DYRK2 playing diverse roles in cellular growth, proliferation, and developmental processes with a focal point being its role in cancer." (PMID 33376136, 2021). "Intriguingly, DYRK2 KO cells were significantly more sensitive to the proteasome inhibitor, bortezomib, suggesting DYRK2 could be a possible therapeutic target for treatment of cancer." (PMID 33376136, 2021). "Besides modulating substrate phosphorylations, transcriptional and epigenetic mechanisms of DYRK2 regulation have also been proposed for some cancers." (PMID 33376136, 2021). "Together, DYRK2 regulates proteostasis and promotes protumorigenic survival for specific cancers." (PMID 33376136, 2021). "However, with conflicting and contradictory reports across different cancers, the overarching role of DYRK2 remains enigmatic." (PMID 33376136, 2021). "Hence, stratification of cancer subtypes before assigning molecular functions to DYRK2 is important." (PMID 33376136, 2021). "Because cancer cells harbor significantly higher misfolded proteins than normal cells, targeting DYRK2 could indeed tip the scales for proteostasis in malignant cells and provide a significant therapeutic window for targeting specific cancers." (PMID 33376136, 2021). "Specific cancer (sub)types coupled to spatiotemporal interactions with substrates could decide the procancer or anticancer role of DYRK2." (PMID 33376136, 2021). "With such high profile, oncology-related substrates, could the function of DYRK2 differ based on cancer type or cell type?" (PMID 33376136, 2021). "In conclusion, we found that certain cancer-related point mutations and the non-cancer-related catalytically inactive Dyrk2-mutant cause a disassembly of the kinase core module revealed by the both complementary interaction approaches AP–MS and BioID–MS." (PMID 32678104, 2020). "Moreover, we found that DYRK2 modulation by chemotherapeutic agents has a relevant effect on the viability, motility and invasion capacity of cancer cells expressing NOTCH1." (PMID 31605148, 2020). "In agreement, DYRK2 knockdown increases cancer cell growth and invasion." (PMID 31605148, 2020). "Cancer: DYRK2 expression in cancer may vary widely depending on the tissue as well as on the expression at the RNA or protein level." (PMID 32462403, 2020). "The posterior functional characterization of these data through an over-representation analysis has allowed us to have a global vision of the contribution of DYRK2 to different cell functions, amongst which we can mention “Pathways in cancer”, “Cellular response to stress”, or “ATM pathway”." (PMID 32462403, 2020). "Agents that transiently reactivate DYRK2 could therefore prove a valuable adjunct to therapy, by promoting the deterioration and death of these cancer stem cells." (PMID 33067577, 2020). "There is evidence that DYRK2 is involved in carcinogenesis through different mechanisms, including regulation of the G1-to-S-phase transition during cell division, epithelial-mesenchymal transition, and cancer cell stemness." (PMID 33067577, 2020). "In addition, blocking RPT3 Thr-25 phosphorylation or knocking down DYRK2 resulted in slower proliferation of human cells, while overexpression of DYRK2, as seen in several cancer types, showed opposite results." (PMID 31380390, 2019). "In addition, DYRK2 gene is amplified in a considerable fraction of cancers and its mRNA level negatively correlates with clinical outcome of breast cancer patients." (PMID 28258412, 2017). "Although the role of DYRK2 in cancer progression remains unclear, a lower expression in invasive tumors has been described." (PMID 26580787, 2015).
cancer (continued). "Thus, dual targetting of HSF1 and its upstream regulator DYRK2 may represent a novel approach to evade drug-resistance, and reduce cancer burden in vivo." (PMID 36622366, 2023). "In addition, DYRK2 may represent a promising therapeutic target in this cancer type, although further studies will be needed to validate this hypothesis." (PMID 36577753, 2022). "This demonstrated that DYRK2 may have distinct effects on different cancer types." (PMID 36104345, 2022). "Therefore, DYRK2 may play different functions to influence patient prognosis and could be a novel target for cancer therapy in different cancer types." (PMID 36104345, 2022). "Importantly, this new link between DYRK2 and HSF1 appears to be relevant in TNBC patients as DYRK2 levels correlate positively with HSF1 nuclear levels, and negatively associate with cancer-specific survival and time to recurrence, supporting a pro-tumoural role for DYRK2 in TNBC." (PMID 33268814, 2021). "Thus, DYRK2-mediated downregulation of IFN signaling could play a major oncogenic role in triggering immunotherapy resistance in various cancers." (PMID 33376136, 2021). "However, in TNBC samples, high nuclear DYRK2 levels significantly associated with reduced cancer-specific survival but not with overall survival." (PMID 33268814, 2021). "For this study, we chose the CMGC kinase Dyrk2 as prototypical kinase module for the development and application of this proteomic workflow because of its central role in the assembly of a multi-subunit protein complex and its putative involvement in cancer progression." (PMID 32678104, 2020). "Therefore, simultaneous targeting of DYRK2 and the proteasome may be a promising combinatorial approach for treating certain cancers, as supported by preliminary data from ongoing research." (PMID 28258412, 2017). "Interestingly, the role of DYRK2 in human cancer remains controversial." (PMID 27532268, 2016). "In summary, these findings indicate that DYRK2 reduces USP28 stability at the protein level, with a potential role in cancer." (PMID 40858801, 2026). "In cancer, curcumin’s effectiveness is determined by examining its interaction with pivotal proteins like CDK2, CK2α, GSK3β, DYRK2, and EGFR, among others." (PMID 38474160, 2024). "These DNAm sites were mapped to genes that play mechanistic roles in multiple cancers, such as cg06513015 on ERV3-1, cg09516963 on DYRK2, cg26919182 on PPP1R12B, and cg17612569 on GABPA and ATP5J." (PMID 36966332, 2023). "The samples were then dichotomised into high and low levels groups for DYRK2 and HSF1 in relation to a cut-off, determined using a receiver operating characteristic (ROC) curve, with cancer death as an endpoint." (PMID 33268814, 2021). "A better understanding of the mechanisms of GEM indicate that it activates HIPK2, p38 MAPK, DYRK2 and PKC kinases, which are involved in p53Ser46 phosphorylation, executing cell apoptosis in response to DNA damage in various cancers." (PMID 33531986, 2021). "To confirm that re-expression of miR-146b-3p can regulate the expression of DYRK2 and GIL2, we first detected DYRK2 and GIL2 in the 12 matched normal and cancer tissues by RT-PCR and western blot." (PMID 33995647, 2021). "The substrates of DYRK2–EDVP exhibit both protumorigenic and antitumorigenic roles in various cancers thus adding further complexity." (PMID 33376136, 2021). "Our data show that DYRK2 activates the pro-survival HSF1 pathway providing a support mechanism and a survival advantage to cancer cells." (PMID 33268814, 2021). "First, DYRK2 regulation of c-Jun, c-Myc, Rpt3, TERT, and katanin p60 reveals the implication of this kinase in cell-cycle-mediated cancer development." (PMID 32462403, 2020).